RTF2 (replication termination factor 2)
Description:
Replication termination factor which is a component of the elongating replisome (Probable). Required for ATR pathway signaling upon DNA damage and has a positive activity during DNA replication. Might function to facilitate fork pausing at replication fork barriers like the rDNA. May be globally required to stimulate ATR signaling after the fork stalls or encounters a lesion (Probable). Interacts with nascent DNA.
Synonyms: C20orf43; RTFDC1; HSPC164; CDAO5; SHUJUN-3
Tractability: PROTAC: ubiquitination databases record sites on it.
Gene: Protein-coding gene on chromosome 20 (56,468,585 to 56,519,449, forward strand). Ensembl gene ENSG00000022277.
Subcellular location: Chromosome
Subcellular location (Human Protein Atlas): Nucleoli; Nucleoplasm
Gene Ontology:
Molecular function: DNA binding; protein binding
Biological process: cellular response to hydroxyurea; regulation of DNA stability
Cellular component: chromosome; nucleolus; nucleoplasm; replication fork; nucleus
Genetic constraint (gnomAD): Loss-of-function variants: 16 observed, 30.16 expected, observed/expected ratio (o/e) 0.53, 90% interval 0.36 to 0.81. The upper end of that interval is the gene's LOEUF score, 0.81, which puts it in group 3 of 6, group 1 being the genes least tolerant of losing a copy. Missense variants: 265 observed, 316.73 expected, observed/expected ratio (o/e) 0.84, 90% interval 0.76 to 0.93. Synonymous variants: 114 observed, 118.6 expected, observed/expected ratio (o/e) 0.96, 90% interval 0.82 to 1.12.
Homologues: Orthologues: chimpanzee RTF2 (99% identical), macaque RTF2 (97% identical), pig RTF2 (92% identical), rabbit RTF2 (90% identical), mouse Rtf2 (88% identical), dog RTF2 (86% identical), guinea pig RTF2 (86% identical), tropical clawed frog rtf2 (66% identical), rat Rtfdc1 (64% identical), zebrafish rtf2 (57% identical), Caenorhabditis elegans tads-1 (38% identical), Drosophila melanogaster CG6443 (37% identical).
Diseases named in the same sentence as RTF2 in open-access papers:
RTF2 is named in the same sentence as 4 diseases in open-access papers, as found by Europe PMC text mining. Sharing a sentence is not in itself a finding about the gene and the disease. The quoted sentences say what the papers report.
viral infection (2 papers, 2020 to 2023). "Recently, Rtf2 has been implicated in a number of additional physiological functions and pathologies including restriction of viral infection and a possible causal factor for Alzheimer’s disease in humans." (PMID 37615341, 2023). "Future studies investigating whether RTF2 interacts with viral RNAs might reveal how RTF2 restricts virus infection, which may be testable in an in vitro replication assay with purified components." (PMID 32878895, 2020).
infection (2 papers, 2020 to 2022). The state of being infected such as from the introduction of a foreign agent such as serum, vaccine, antigenic substance or organism. "RTF2-KO cells also displayed elevated luciferase activity in the minigenome reporter assay, an assay that is based on transfected plasmids instead of infection with live viruses and, hence, that bypasses all the earlier steps in the viral life cycle." (PMID 32878895, 2020). "We found that IFN pretreatment (which reduces overall infection rates) enhances the fold increase in infection between RTF2-KO cells and RTF2-rescued cells." (PMID 32878895, 2020). "All three approaches suggest that an intact IFN signaling pathway is required to observe the effect of RTF2 knockout (KO) on infection." (PMID 32878895, 2020). "Among the top hits in our primary screen, RTF2 (also known as RTFDC1) was found to be an antiviral gene, with little being known about its cellular function or role in infection." (PMID 32878895, 2020). "We also tracked the kinetics of infection by monitoring NP mRNA levels over time and noticed that the difference in NP mRNA levels between RTF2-KO cells and RTF2-rescued cells could be detected even at 4 h postinfection (hpi)." (PMID 32878895, 2020). "To test the effect of mislocalizing RTF2 during IAV infection, we quantified infection based on surface HA expression and NP mRNA levels." (PMID 32878895, 2020). "We found no changes in infection when RTF2 was overexpressed, indicating that RTF2 alone is not sufficient to restrict viral replication." (PMID 32878895, 2020). "While we do not know if RTF2 KO also affects early steps of infection, we found that RTF2-KO cells exhibited a higher rate of primary transcription (rather than a lower rate of degradation)." (PMID 32878895, 2020). "Given that RTF2 may play a role in positively regulating the IFN response, we hypothesized that RTF2 KO should result in higher infection rates by other viruses, especially viruses that are susceptible to the effects of IFN signaling." (PMID 32878895, 2020). "To investigate the dependence on IFN, we infected wild-type A549, RTF2-KO, and RTF2-rescued cells in the presence or absence of IFN and then measured the infection rates based on surface HA levels." (PMID 32878895, 2020).
RTF2 also shares sentences with these, for which no sentence is quoted: Alzheimer disease (1 paper); tumor (1).